INS (insulin)
Diseases named in the same sentence as INS in open-access papers (continued):
Sharing a sentence is not in itself a finding about the gene and the disease.
Insulin resistance (continued). "Despite targeting VEGFB as a novel treatment for insulin resistance and type 2 diabetes, our results showed that the knockdown of VEGFB did not affect the glucose tolerance and insulin tolerance." (PMID 35886871, 2022). "When insulin is absent, GLUT4 is misdistributed, and it fails to transport to the plasma membrane, which leads to early signs of insulin resistance and DM type 2." (PMID 35454166, 2022). "Our cell culture data conflicts with a series of mouse studies reporting that treatment with OSM improved insulin sensitivity, while the absence of OSM signalling in adipocytes gave rise to insulin resistance." (PMID 35531859, 2022). "Due to the development of insulin resistance in T2DM and the lack of exogenous insulin production in T1DM, the cellular uptake of glucose is blunted despite high blood glucose levels." (PMID 35250632, 2022). "Despite no direct measures of insulin resistance, it is plausible that the DXM cohort became resistant to insulin as evidenced by daily glucose levels outside of the intended target range (4–8 mM)." (PMID 36083870, 2022). "Thus, enrolled patient with chronic kidney disease, have higher insulin resistance, higher inflammatory state, and higher incidence of AKI which might have contributed to a higher mortality and morbidity rate in the group of patients who were treated with insulin at home." (PMID 35725489, 2022). "Despite there being partially missing data, such as fasting insulin and HOMA-IR, we showed that these metabolic features are NAFLD-specific, regardless of insulin resistance and obesity." (PMID 36144285, 2022). "Fasting insulin levels were also elevated in PCOS and non-PCOS subjects with obesity, highlighting possible insulin resistance." (PMID 36204478, 2022). "In rats, the negative effect of BCAA excess on insulin sensitivity is accompanied by increased mTORC1 activity in skeletal muscle, and this BCAA-induced insulin resistance is reversible by rapamycin, an acute inhibitor of mTORC1." (PMID 36361511, 2022). "Although M-ORX did not develop peripheral insulin resistance, peripheral insulin resistance was detected in F-OVX and the HFD groups (M-HFS, M-HFO, F-HFS, and F-HFO), as demonstrated by increased levels of insulin and HOMA index." (PMID 35301277, 2022). "As increased insulin resistance, rather than beta cell function, is related to an insufficient response to a low carbohydrate diet, we speculate that insulin sensitizers rather than insulin therapy may be the most targeted therapeutic modality in diet-insensitive GDM." (PMID 35745174, 2022). "It has been proven that insulin resistance was successfully induced, and no increase in insulin-stimulated glucose uptake (ISGU) was observed in insulin-resistant adipocytes." (PMID 35684107, 2022). "The glucose and insulin levels of the subjects are not abnormal on average, but when the HOMA-IR index is used, it is evident that insulin resistance (prediabetes) is likely in > 50% of men and > 40% of women." (PMID 36447164, 2022). "In vitro studies show that treatment with obese ATM-exosomes led to glucose intolerance and insulin resistance in myocytes, while lean ATM-exosomes treatment improved systemic insulin sensitivity; however, no protein cargoes in ATM-exosomes were reported." (PMID 36293266, 2022). "While whole body insulin sensitivity did not change, homeostasis model assessment of insulin resistance (HOMA-IR) and the hepatic insulin resistance index (HIR) increased during overfeeding." (PMID 35614978, 2022). "Second, insulin resistance, as a criterion of MAFLD diagnosis, was not assessed in our study due to the lack of serum insulin data in CKB." (PMID 36035906, 2022). "Insulin resistance with the glucose clamp was not changed, but the HOMA-IR and insulin sensitivity indices were significantly improved." (PMID 35115614, 2022). "The surrogate marker for insulin sensitivity, QUICKI, indicated that the consumption of the WD, but not the SSB, induced insulin resistance." (PMID 35276952, 2022).
Insulin resistance (continued). "The levels of FBG, INS, and HOMA-IR, the pointer of T2DM insulin resistance, have a negative correlation with deoxycholic acid, tetrahydroaldosterone-3-glucuronide, enterolactone, 12-Ketodeoxycholic acid, and other metabolites." (PMID 36353458, 2022). "However, insulin resistance was estimated using HOMA-IR, which has limitations, and it is possible that true differences could have been detected if a glucose tolerance test or a direct measure of insulin sensitivity (e.g., hyperinsulinemic euglycemic clamp) had been used." (PMID 36118754, 2022). "Plasma insulin was not measured for this cross; thus HOMA-IR (Homeostatic Model Assessment for Insulin Resistance) and the role of insulin resistance in the etiology of type 2 diabetes and atherosclerosis were unable to be determined." (PMID 36078077, 2022). "Although weekly blood samples did not demonstrate any alterations to insulin or glucose parameters, the responses to the IVGTT suggest that the HF diet was successful in stimulating a degree of insulin resistance in these pigs." (PMID 35804599, 2022). "About 40% of patients met the PR definition by stimulated C-peptide but not GA/insulin dose or IDAGA, who showed dyslipidemia and higher insulin resistance." (PMID 35928900, 2022). "Another consideration is that we measured fasting insulin and calculated HOMA-IR only and did not use the euglycemic clamp to depict insulin resistance more accurately." (PMID 35682232, 2022). "Beta cell function (HOMA2-%B, p = 0.10), insulin resistance (HOMA2-IR, p = 0.18) and insulin sensitivity (HOMA2-%S, p = 0.51) did not vary significantly between the timepoints." (PMID 35160113, 2022). "However, standards for assessing insulin resistance in children in the clinical setting are still lacking, and insulin-derived indexes of insulin resistance/sensitivity are affected by methodological issues, such as the poor standardization of insulin measurement." (PMID 34142364, 2022). "Knockout of the GABAB receptor improved glucose tolerance and increased insulin content in the islets of mice, but constitutive absence of the GABAB receptor induced insulin resistance in mice." (PMID 35669692, 2022). "The consumption of a diet with a daily avocado altered abdominal fat distribution from baseline to 12 weeks in women but there were no improvements in body weight, insulin resistance (HOMA-IR), insulin sensitivity, or β-cell function in either men or women." (PMID 34959933, 2021). "The Bza-induced decrease in fasting plasma glucose found in obese mice was accompanied by a decrease in insulin resistance index (attested by relative murine HOMA-IR), while circulating insulin was not altered." (PMID 34444782, 2021). "However, paternal insulin resistance was not independently associated with offspring birthweight in a birth-cohort study of 986 UK parent–offspring trios, and there was a positive correlation between paternal HOMA-IR and umbilical cord insulin levels in 644 fathers and babies." (PMID 33569631, 2021). "Along with the in vitro glucose uptake study results using insulin-resistant C2C12 cells, it is evident that PEG-BHD1028 effectively regulates glucose metabolism by lowering insulin resistance without stimulating insulin secretion." (PMID 33477324, 2021). "A second limitation was that insulin concentrations were not measured during the OGTT test, to assess insulin resistance." (PMID 34684408, 2021). "On the contrary, mice lacking Gpx1 were protected from insulin resistance induced by a high-fat diet, while administration of N-acetylcysteine (NAC), the Gpx1 substrate, rendered them insulin-resistant and increased fasting glucose levels." (PMID 33810179, 2021). "Overall, 7 days of HFHC diet did not induce changes in whole-body insulin sensitivity (Matsuda ISI), or indices of hepatic or muscle insulin resistance." (PMID 32789769, 2021).
Insulin resistance (continued). "The European Group for the Study of Insulin Resistance (EGIR) shared the sentiment, requiring non-diabetic individuals to have insulin levels in the 75th percentile or higher, but excluded the microalbuminuria criterion." (PMID 34520483, 2021). "All are strongly related to insulin resistance and type 2 diabetes (T2DM) in adults (glycine inversely) and are independent of biological and methodological variations in insulin assays." (PMID 34084151, 2021). "Firstly, SA treatment attenuated renal inflammation and improved insulin resistance in both obese WT and TRPV1−/− mice, indicating that the beneficial effects of SA on insulin sensitivity are independent of TRPV1." (PMID 34069822, 2021). "In our study, we used indices of insulin action on glucose metabolism (Si, but also HOMA) and found that insulin resistance is not accompanied by abnormalities in lipid and lipoprotein metabolism in the absence of obesity." (PMID 33718425, 2021). "Determining insulin resistance in T2DM is not simple, especially in patients who are treated with exogenous insulin because of exogenous hyperinsulinaemia." (PMID 34577866, 2021). "We found BMI unrelated insulin resistance in PCOS individuals and a significant correlation between insulin level and free androgen index, irrespective of weight." (PMID 33750349, 2021). "Insulin resistance, typical for T2DM, is a condition in which the blood concentration of insulin does not exert its biological activity." (PMID 34451903, 2021). "Insulin resistance was an important feature of PCOS, but insulin release test was not routinely performed for the aged tubal infertility patients, but only in overweight or obese patients." (PMID 35111134, 2021). "In addition, our other data supports that knocking out MMP12 in ApcMin/+ mice may reduce insulin levels or increase insulin sensitivity, which could contribute to reversing insulin resistance, while it was not related to the basic function of islets based on results of H&E staining and IHC staining." (PMID 34863141, 2021). "Previous studies have shown that FGF21 can improve insulin resistance in peripheral tissues of patients with T2DM, leading to decrease glucose levels independent of insulin." (PMID 34769010, 2021). "It seems that while the negative feedback of the STAT3 signaling delays the insulin/IGF-1-induced aging process, it nonetheless elicits insulin resistance and diabetes." (PMID 34476533, 2021). "Insulin stimulation did not increase glucose uptake in 3T3-L1 cells after TNFα treatment, while DHM prevented the TNFα-induced insulin resistance." (PMID 34650665, 2021). "These events eventually stimulate the insulin signaling pathway by activating insulin receptor and GLUT-4 (data not shown) and thus reverse insulin resistance." (PMID 33917607, 2021). "Nevertheless, GSK0660 treatment notably increased serum levels of leptin, insulin, and triglyceride in rats, without affecting glucose levels, suggesting that GSK0660 induced insulin resistance in 3-month-old Wistar rats." (PMID 33924880, 2021). "At both weeks 9 and 32, there were no group differences in fasting serum insulin concentrations or HOMA-IR, a measure of insulin resistance." (PMID 33735324, 2021). "Insulin resistance, represented as 2-h 75 g GTT insulin ≥ 100 μU/mL, was not significant in both models." (PMID 33782517, 2021). "In adults, it is accepted that obesity determines the onset of insulin resistance by impairing insulin signaling, and non-esterified fatty acids (NEFA) have been postulated as the link between obesity and insulin resistance." (PMID 35071145, 2021). "In short-term studies, insulin resistance remained higher in women with GDM previously, while their insulin secretion rates were similar to the previous nondiabetic pregnant women." (PMID 32184821, 2020). "Insulin resistance (calculated via HOMA-IR, an index derived from fasting glucose and insulin levels) was observed in the CRF-OE mice at 19 weeks but not at 7 weeks." (PMID 32049987, 2020).
Insulin resistance (continued). "The irisin lacking mice had hyperlipidemia and insulin resistance, reduced HDL-cholesterol level, increased LDL-cholesterol level, and decreased insulin sensitivity." (PMID 33060792, 2020). "In order to assess the relationship between bilirubin and insulin sensitivity further, the subjects (n = 38) in the IGR/T2DM group were classified into two categories: patients with or without insulin resistance based on the cutoff value M = 4.9 mg/kg·min." (PMID 32802055, 2020). "Given that MAM harbors several proteins responsible for the insulin signaling, and its integrity is also required for insulin action, it is not surprising that MAM alternations occur in the presence of insulin resistance and T2DM." (PMID 33195204, 2020). "However, in animal models, the development of insulin resistance in response to HFD is highly heterogeneous, and a total fat mass is not its direct predictor, suggesting that changes that take place in other tissues may play a role in determining insulin sensitivity." (PMID 32397353, 2020). "Results from our study showed that insulin and glucose levels, as well as HOMA-IR and -β, were not different among protein intake groups, indicating that insulin resistance was similar among groups." (PMID 32650580, 2020). "It should be noted that the selectively blocking of ERK signaling is documented to be beneficial for the alleviation of insulin resistance in T2D, and the absence of JNK has been determined to improve the insulin sensitivity." (PMID 32928312, 2020). "Our current data implicate IMAT in paretic and nonparetic skeletal muscle in insulin resistance by the glucose clamp and support our earlier finding of the relationship between higher IMAT and higher fasting insulin concentrations in chronic stroke." (PMID 33375333, 2020). "No marked change was observed in fasting insulin (FINS), glycosylated hemoglobin (HbA1c), and HOMA of insulin resistance (HOMA-IR) levels." (PMID 32384902, 2020). "The homeostatic model assessment of insulin resistance (HOMA-IR) is a relatively extensive method used in research, but the lack of standardized insulin assays has hindered its development." (PMID 32703284, 2020). "A major limitation of the present study was that we used HOMA‐β to evaluate ISF, which is affected by obesity‐ and age‐related insulin resistance, such that ISF and insulin sensitivity are not clearly distinguished using this measure." (PMID 33102766, 2020). "The lack of insulin response however is of particular interest in T2DM and obese individuals for whom insulin resistance and/or insufficiency is already a problem." (PMID 32977648, 2020). "Signaling of insulin occurs via insulin receptor substrate 2 (IRS2) and is not suppressed during insulin resistance, while signaling via IRS1 for counterregulatory mechanisms, including local NO production, is impaired." (PMID 32819363, 2020). "In the development of insulin resistance and type 2 diabetes, GLUT4 fails to translocate to plasma membrane in response to insulin." (PMID 32253813, 2020). "Consistent with the serum glucose and insulin concentrations, HOMA-IR, an index of insulin resistance, was higher in ORX-CON than Non-ORX-CON, whereas ORX-CFW and ORX-MBW reduced HOMA-IR compared to the ORX-CON." (PMID 33371279, 2020). "Alteration in insulin sensitivity, however, has not yet been assessed in the in vitro STZ model, thus the development of neuronal insulin resistance remains to be clarified." (PMID 31858268, 2020). "However, in females, gonadectomy inducedthe development of insulin resistance, and exogenous estradiolnormalized insulin sensitivity, while in males, gonadectomyand estradiol did not have a significant effect on the studiedparameters of insulin sensitivity (blood glucose and insulinlevels, HOMA-IR)." (PMID 33659826, 2020).
Insulin resistance (continued). "Our obtained data here also showed that the EtOAc extract can reduce STZ-NA induced problems by lowering blood glucose levels and improving indexes related to insulin resistance, including HOMA-IR, HOMA-β, QUICKI, and DI without changing insulin levels." (PMID 33489029, 2020). "We report here that the lack of α7 nAChR leads to insulin resistance in 25-week-old mice as shown by markedly reduced insulin-stimulated glucose uptake in EDL skeletal muscle, supporting α7 nAChR involvement in insulin sensitivity." (PMID 32708537, 2020). "Despite the link between type 2 diabetes and CNS insulin resistance, the effect of PPARγ agonists at the BBB on insulin transport have not been explored." (PMID 32704569, 2020). "In line with this, a constitutive active form of JNK overexpressed in hypothalamic Agrp neurons does not impair hypothalamic insulin action and JNK inhibition did not affect PA- and CHO + PA-induced insulin resistance in our study." (PMID 32456175, 2020). "There exist various methods to assess insulin resistance with insulin measurements such as HOMA IR; yet, as in the case of insulin measurement, it is not readily available in most places." (PMID 33376488, 2020). "Insulin signaling required for Nrf2 inhibition occurs via the MAP kinase pathway and thus is not mitigated by insulin resistance." (PMID 32819363, 2020). "In a recent meta-analysis, including six RCTs, it was found that vitamin D supplementations improved insulin resistance and LDL cholesterol, but had no beneficial effect on FPG, insulin, HbA1c, total-, HDL-cholesterol, and triglycerides concentrations." (PMID 33036170, 2020). "Insulin resistance was induced in nondiabetic adipocytes and myocytes by either TNF exposure or treatment with high glucose and high insulin; lamivudine prevented insulin resistance induced in both these models." (PMID 32968070, 2020). "GSK-3β is an insulin signaling regulator that plays an important negative regulatory role in diabetic insulin signaling, and its enhanced expression exacerbates T2DM insulin resistance." (PMID 32714403, 2020). "The physiological insulin resistance of late-pregnancy is accentuated in women developing GDM, thus their insulin secretion is not sufficient to maintain euglycemia, leading to glucose intolerance." (PMID 30717458, 2019). "Thus, the aims of this study were to investigate in DM skeletal muscle biopsies if beyond INSR missplicing, altered IR protein expression could play a role in insulin resistance and to verify if the lack of insulin pathway activation could contribute to skeletal muscle wasting." (PMID 30901379, 2019). "The study found that the effect of OOPs intervention on serum insulin in diabetic rats was not obvious, but the HOMA-IR index representing the insulin resistance level was significantly reduced." (PMID 30717466, 2019). "The exacerbated glucose intolerance and hyperglycemia in HFD-treated Nod1beta-cko mice was not due to insulin resistance, because HFD-treated Nod1 Nod1beta-cko mice were not more insulin resistant than the control mice." (PMID 31201384, 2019). "Post-meal exercise, but not the pre-meal exercise, also significantly lowered serum insulin response and homeostatic model (HOMA-IR) assessment of insulin resistance." (PMID 31261978, 2019). "Taking into account the parameters of insulin resistance (OGTT values, HOMA-IR, and fasting insulin), fasting insulin was the best predictor of the non-responsiveness to clomiphene." (PMID 31423417, 2019). "Fourth, insulin resistance was defined by HOM-IR and not by the invasive and time-consuming euglycemic insulin clamp." (PMID 31770376, 2019). "It was found that Brazilian green propolis (900 mg/day) did not improve insulin resistance, hemoglobin A1C, fasting BGL and serum insulin level during eight weeks treatment, but it prevented uric acid elevation and renal dysfucntion in diabetic patients." (PMID 32128099, 2019).